PPP1R13B-DT (PPP1R13B divergent transcript)
Synonyms: HITT; LINC00637
Gene: Long non-coding RNA gene on chromosome 14 (103,847,687 to 103,880,381, forward strand). Ensembl gene ENSG00000258735.
Diseases named in the same sentence as PPP1R13B-DT in open-access papers:
PPP1R13B-DT is named in the same sentence as 6 diseases in open-access papers, as found by Europe PMC text mining. Sharing a sentence is not in itself a finding about the gene and the disease.
PPP1R13B-DT shares sentences with these, for which no sentence is quoted: cancer (3 papers); ataxia telangiectasia (1); cervical cancer (1); insomnia (1); liver cancer (1); tumor (1).